DNMT3A (DNA methyltransferase 3 alpha)
Diseases named in the same sentence as DNMT3A in open-access papers (continued):
Sharing a sentence is not in itself a finding about the gene and the disease.
myeloid leukemia (12 papers, 2013 to 2024). A clonal proliferation of myeloid cells and their precursors in the bone marrow, peripheral blood, and spleen. "Hotspot mutation of the DNA methyl transferase-encoding gene DNMT3A is a frequent and early event associated with poor patient survival in myeloid leukemias." (PMID 38175731, 2024). "In this study, we further assessed the genetic characteristics of DNMT3A mutations in adult patients with de novo CN‐AML using targeted NGS with a panel of 34 genes associated with myeloid leukemia." (PMID 36912186, 2023). "Combined heterozygous loss of Tet2+/– and Dnmt3a+/– and expression of Flt3ITD/WT results in a transplantable myeloid leukemia." (PMID 36073548, 2022). "Combined heterozygous loss of Tet2 (Tet2+/–) and Dnmt3a (Dnmt3a+/–) and expression of Flt3ITD/WT (Tet2+/– Dnmt3a+/– Flt3ITD/WT) results in an aggressive lethal myeloid leukemia." (PMID 36073548, 2022). "Heterozygous mutations of DNMT3A have been observed to lead to the development of myeloid leukaemias, implying that DNMT3A qualifies as a haploinsufficient tumour suppressor gene." (PMID 31405121, 2019). "Given that the human DNMT3A R882H (mouse R878H) is a driver mutation for clonal hematopoiesis and one of the major risk factors for myeloid leukemia progression, it is of great importance to obtain small molecule(s) inhibiting hematopoietic cells carrying DNMT3A R882H." (PMID 34663800, 2021). "Interestingly, UP-ALL13 was found to harbor a heterozygous R882H DNMT3A mutation typically found in myeloid leukemia." (PMID 30304769, 2018). "Aberrant DNA methylation mediated by mutations of TET2, WT1, DNMT1, DNMT3A, and DNMT3B genes is correlated to the pathogenesis of myeloid leukemia." (PMID 37375831, 2023). "Further work must be done to find the importance of having specifically the DNMT3A and PTPN11 genes mutated together, but these are two commonly mutated genes in myeloid leukemia that we have now shown leads to accelerated disease." (PMID 29464054, 2018). "Because DNMT3A and PTPN11 mutations are found in combination in AML and JMML patients, our double mutant mice provide a novel clinically relevant model for developing and evaluating therapies for myeloid leukemia." (PMID 29464054, 2018).
schizophrenia (12 papers, 2014 to 2026). A major psychotic disorder characterized by abnormalities in the perception or expression of reality. "Among de novo methyltransferases the DNMT3A rs2289195 was found to be associated at genotypic level (P = 0.013) with schizophrenia." (PMID 24859147, 2014). "In addition to the reports that related overexpression of DNMT1 in brain samples from schizophrenia patients, certain alleles of Dnmt1, Dnmt3A, and Dnmt3L have been found to be associated with schizophrenia." (PMID 26798355, 2016). "Neurodevelopmental regression and psychotic disorders, including schizophrenia, have been documented in DNMT3A-related TBRS, prompting recommendations for lifelong psychiatric follow-up." (PMID 41384217, 2025). "Further analyses revealed that two of these variants (rs2304429 and rs11079983) are predicted to alter the expression of specific genes (DNMT3A, ASB16, and ASB16-AS1) in brain regions previously implicated in schizophrenia and treatment response." (PMID 31354789, 2019). "Consistent with this expectation, overexpression of DNMT3A was also observed in GABAergic neurons of schizophrenia patients." (PMID 26798355, 2016). "Observations from association analyses of SNPs in DNMT1, DNMT3A, DNMT3B, and DNMT3L indicated that DNMT1 rs2114724 and rs2228611 were strongly associated with schizophrenia at allelic and genotypic level." (PMID 24859147, 2014). "We screened for polymorphisms in DNA methyltransferases, DNMT1, DNMT3A, DNMT3B and DNMT3L in 330 schizophrenia patients and 302 healthy controls for association with Schizophrenia in south Indian population." (PMID 24859147, 2014). "Association analysis of DNMT1, DNMT3A, DNMT3B and DNMT3L polymorphisms are summarised by -Log P value for schizophrenia in a South Indian population." (PMID 24859147, 2014). "The aim of the present study was to identify the role of genetic variants in DNA MethylTransferases such as maintenance methyltransferase gene (DNMT1) and genes for de novo methyltransferases (DNMT3A & 3B) and DNMT3L in predisposing to schizophrenia." (PMID 24859147, 2014). "Regulation of DNMT3A depends on miR-29 expression pattern in postnatal brain during lifespan so that downregulation of miR-29 associated with increased CH methylation in genes such as CHL1, FZD3, and SOX5 which are associated with schizophrenia." (PMID 38705955, 2024). "DNA methyltransferase-dependent DNA methylation in developing interneurons seems to be implicated in schizophrenia, as prenatal stress in mice elevates Dnmt1 and Dnmt3a expression in GABAergic interneurons and induces behaviors indicative of a schizophrenia-like phenotype in their offspring." (PMID 33041771, 2020). "In another postmortem study of the DLPFC in schizophrenia, miR-132 was observed to be dysregulated and this was supported by the altered expression of its target genes, including DNMT3A, GATA2, and DPYSL3, which are known to be related to the development of the nervous system and schizophrenia." (PMID 32764320, 2020). "Moreover, elevated hippocampal DNMT3A expression has been reported in the postmortem brain of schizophrenia patients." (PMID 32726795, 2020). "In addition, an increased mRNA expression of DNA methyl-transferases (DNMT1 and DNMT3a) has been observed in schizophrenia." (PMID 25206360, 2014).
diabetes (11 papers, 2017 to 2025). "Fourth, the Neurog3+ progenitors that are exposed to maternal overnutrition, an established risk factor for diabetes, express lower levels of DNMT3a and Myt1." (PMID 38496675, 2024). "In addition to the abnormal expressions of the methyltransferases DNMT3a and DNMT3b mentioned in our previous study, the specific mechanism may be related to vitamin and folic acid deficiency caused by diabetes." (PMID 31781662, 2019). "Studies have shown that transient Dnmt3a overexpression attenuated denervation- and diabetes-induced muscle atrophy." (PMID 40151644, 2025). "We observed that Dnmt3a-Tg muscle had decreased FoxO signaling and was protected against starvation-induced muscle atrophy, as reported in denervation- and diabetes-induced muscle atrophy." (PMID 40151644, 2025). "In diabetes, Dnmt3a modulates the Pten/Akt pathway and prevents muscle atrophy." (PMID 40151644, 2025). "Indeed, these results suggested that diabetes-induced hyperglycemia led to down-regulation in DNMT3a activity in spermatogonia and spermatocytes of T1D-induced diabetic rats when compared to controls." (PMID 38164482, 2024). "Considering DNMT3a is down-regulated in diabetes-induced hyperglycemia, it might be expected that this reduction in DNMT3a expression results in HDAC enzyme down-regulation and HAT enzyme up-regulation, leading to hypomethylation." (PMID 38164482, 2024). "Contrary to the fact that aging seems to increase DNA methylation in skeletal muscle and exercise rejuvenates DNA methylome in skeletal muscle, transient overexpression of muscle Dnmt3a, responsible for increasing DNA methylation, could suppress denervation- and diabetes-induced muscle atrophy." (PMID 40151644, 2025). "From a biological perspective, mutations involved with leukemogenesis (DNMT3A, TET2, and ASXL1) are also enriched in patients with diabetes and atherosclerotic disease but without cancer." (PMID 33709085, 2020).
endometriosis (11 papers, 2012 to 2025). The growth of functional endometrial tissue in anatomic sites outside the uterine body. "Here, we propose that exposure to PCB126 drives the upregulation of DNMT3A, leading to the establishment of endometriosis-associated DNA methylation patterns that promote disease progression." (PMID 40951281, 2025). "Our study demonstrated that PCB126 elevates DNMT3A expression in endometriotic lesions, contributing to establishing endometriosis-associated DNA methylation." (PMID 41054802, 2025). "In this context, our endometrium-specific Dnmt3a knockout mouse model provides critical insight, showing that DNMT3A plays a causal role in endometriosis progression." (PMID 40951281, 2025). "Identifying the causal factor responsible for DNMT3A upregulation in endometriotic lesions is a key question for understanding the molecular etiology of endometriosis progression." (PMID 40951281, 2025). "PCB-126 promotes endometriosis progression through coordinated activation of the AXL/ERβ/DNMT3A axis, disrupting estrogen-mediated epigenetic regulation and inducing endometriosis-associated immunoinflammatory responses." (PMID 40951281, 2025). "Our study demonstrated that PCB126 elevates DNMT3A expression in endometriotic lesions, contributing to the establishment of endometriosis-associated DNA methylation." (PMID 40951281, 2025). "Therefore, the PCB126/AXL/GAS6/ERβ axis represents a key mechanism underlying the induction of endometriosis-associated DNA methylation via DNMT3A." (PMID 40951281, 2025). "Since EMT plays a critical role in endometriosis progression, the elevation of ciliogenesis resulting from Dnmt3a loss may suppress disease progression by inhibiting the EMT process." (PMID 41054802, 2025). "Therefore, the PCB126/AXL/GAS6/ESR2 axis represents a key mechanism underlying the induction of endometriosis-associated DNA methylation via DNMT3A." (PMID 41054802, 2025). "Our findings establish a mechanistic connection between environmental PCB126 exposure and endometriosis progression via the AXL/ESR2/DNMT3A axis." (PMID 41054802, 2025). "Dnmt3a regulates inflammatory immune response in ectopic lesions for the progression of endometriosis." (PMID 40951281, 2025). "IHC analysis further confirmed that Dnmt3a expression was markedly increased in both the epithelial and stromal compartments of ectopic lesions in mice with endometriosis compared to normal endometrium." (PMID 41054802, 2025). "Immunohistochemical (IHC) analysis further confirmed that Dnmt3a expression was markedly increased in both the epithelial and stromal compartments of ectopic lesions in mice with endometriosis compared to normal endometrium." (PMID 40951281, 2025). "Collectively, these results demonstrate that Dnmt3a plays a critical role in the progression of endometriosis in this mouse model." (PMID 40951281, 2025). "RNA sequencing was then performed on Dnmt3a knockout ectopic lesions and compared to control lesions to define the role of DNMT3A in endometriosis progression." (PMID 40951281, 2025). "Collectively, our study identifies the PCB126/AXL/GAS6/ERβ/DNMT3A axis as a key integrator of endocrine-disrupting chemical (EDC)-mediated endometriosis progression." (PMID 40951281, 2025). "Collectively, these findings suggest that PCB-126 promotes endometriosis progression through coordinated activation of the AXL/ERβ/DNMT3A axis, driving estrogen-mediated epigenetic and immunoinflammatory responses." (PMID 40470214, 2025). "On the other hand, only Dnmt3a was found to be upregulated in eutopic endometria in females with endometriosis compared to that observed in endometriosis-free females." (PMID 24465385, 2014). "We observed markedly increased levels of DNMT3A transcript in eutopic mid-secretory endometrium from women with endometriosis compared to fertile women." (PMID 22233680, 2012).
endometriosis (continued). "We also observed significantly increased levels of DNMT3A transcript in women with endometriosis than fertile women (p = 0.044) and infertile women with tubal occlusion (p = 0.047)." (PMID 22233680, 2012). "RQ-PCR analysis showed significantly increased levels of DNMT3A transcript in eutopic mid-secretory endometrium from women with endometriosis compared to fertile women (p = 0.044) and women with tubal occlusion (p = 0.047)." (PMID 22233680, 2012). "Targeting the AXL/ESR2/DNMT3A axis may represent a novel therapeutic avenue for environmentally induced endometriosis." (PMID 41054802, 2025). "Although elevated DNMT3A levels are associated with endometriosis progression, no direct evidence demonstrates that alterations in DNMT3A directly drive disease progression." (PMID 41054802, 2025). "Furthermore, the PCB-126/ERβ axis upregulated Dnmt3a expression, contributing to inflammation and immune dysregulation within ectopic lesions and thereby exacerbating endometriosis progression." (PMID 40951281, 2025). "This is a key question for understanding Dnmt3a-mediated endometriosis progression." (PMID 40951281, 2025). "To determine whether Dnmt3a plays an essential role in endometriosis progression, we generated an endometrium-specific Dnmt3a KO mouse by crossing floxed Dnmt3a (Dnmt3af/f) with PRCre/+ mice, in which Cre recombinase is expressed in PR-expressing cells." (PMID 41054802, 2025). "Our Dnmt3a knockout mouse model demonstrated that many of these cellular pathways were downregulated in ectopic lesions lacking Dnmt3a, suggesting that DNMT3A is involved in modulating key endometriosis-associated pathways." (PMID 40951281, 2025). "Furthermore, IHC analysis confirmed that PCB126 exposure markedly increased Dnmt3a expression in both epithelial and stromal cells of mouse ectopic lesions compared to vehicle-treated mice with endometriosis." (PMID 40951281, 2025). "Therefore, Dnmt3a represents a promising molecular target for the development of nonhormonal therapies aimed at correcting immune dysregulation in patients with endometriosis." (PMID 41054802, 2025). "Answering this question is critical to understanding DNMT3A-mediated endometriosis progression." (PMID 40951281, 2025). "Although elevated DNMT3A levels are associated with endometriosis progression, there is no direct evidence demonstrating that alterations in DNMT3A drive disease progression." (PMID 40951281, 2025). "The PCB126/AXL/GAS6/ERβ/DNMT3A axis provides a critical clue for understanding how EDCs may epigenetically drive the formation of an inflammatory-immune microenvironment that promotes endometriosis progression." (PMID 40951281, 2025). "To determine whether Dnmt3a plays an essential role in endometriosis progression, we generated an endometrium-specific Dnmt3a knockout (KO) mouse by crossing floxed Dnmt3a ((Dnmt3af/f) with Progesterone Receptor (PR)Cre/+ mice, in which Cre recombinase is expressed in PR-expressing cells." (PMID 40951281, 2025). "Therefore, we focused on elucidating the role of Dnmt3a in the progression of endometriosis." (PMID 41054802, 2025). "In patients with endometriosis, DNMT1, DNMT3A, and DNMT3B are overexpressed in the epithelial component of endometriotic implants compared to normal controls or the eutopic endometrium of women with endometriosis." (PMID 40951281, 2025). "DNMT1, DNMT3A and DNMT3B transcripts in eutopic mid-luteal endometrium from infertile women with endometriosis, fertile women and infertile women with tubal occlusion." (PMID 22233680, 2012). "Collectively, our study demonstrated that exposure to PCB126 indirectly upregulated Dnmt3a through the activation of the AXL/GAS6/ESR2 axis, leading to dysregulation of epigenomic regulation in the endometrium and promoting the progression of endometriosis." (PMID 41054802, 2025).
endometriosis (continued). "The DNMT1, DNMT3A, and DNMT3B expression levels were reported to be elevated in ectopic endometria compared to normal controls or in the eutopic endometrium of women with endometriosis." (PMID 32370117, 2020). "Many studies reported the up-regulated expression of only for the DNMT3A and not for DNMT1 and DNMT3B in the endometriotic tissue which leads to hypermethylation in endometriosis." (PMID 32042366, 2020).
Myelodysplasia (11 papers, 2020 to 2025). Clonal hematopoietic stem cell disorders characterized by dysplasia (ineffective production) in one or more hematopoietic cell lineages, leading to anemia and cytopenia. "In an analysis of Chinese AML patients with myelodysplasia-related changes receiving low-intensity Ven-based treatments, mutated DNMT3A was associated with a higher risk of relapse." (PMID 40867287, 2025). "These preleukemic HSCs harbor mutations associated with myelodysplasia (e.g., of DNMT3A, TET2, and others), which persist in myeloid cells as well as B and T cells but lack the mutations present in leukemic blasts." (PMID 35259128, 2022). "Additionally, recent data demonstrated that myeloid specific mutations including TET2, ASXL1, and DNMT3A can induce inflammasome activation in myelodysplasia and exacerbate inflammation." (PMID 33648567, 2021). "Eight myelodysplasia-associated somatic variants in the BCOR/BCORL1, DNMT3A, ASXL1, CUX1, and ETV6 genes were found in 7 patients (5 AA and 2 MDS-h patients, 17%); neither AA patient had evidence of myelodysplasia at the time of analysis." (PMID 41188636, 2025). "Bone marrow biopsies revealed a clonal cytotoxic T‐LGL population and a DNMT3A mutation without evidence of myelodysplasia or metastatic infiltration." (PMID 40734768, 2025).
breast tumor (10 papers, 2010 to 2023). "Fourteen percent of breast tumors with DNMT3A mutations that metastasized to bone were classified as bone, statistically indistinguishable from the 12% of all breast metastases classified as bone (p = 0.39)." (PMID 32374727, 2020). "Similarly, DNMT3a downregulation in breast tumors (n = 34) associates (p = 0.016237) with a poor disease-specific survival (HR[95% CI] = 0.33[0.07–1.54])." (PMID 28393842, 2017). "One group also reported that DNMT3A was highly expressed in breast tumor tissues than the adjacent normal specimens." (PMID 35620052, 2022). "As we observe in breast tumors in our study, they also found significant anti-correlation between the levels of hsa-miR-29 family members and DNMT3A/B mRNA levels in lung tumors." (PMID 33926515, 2021). "To investigate whether the difference in methylation profiles between breast tumors is related to differences in the DNA methyltransferase (DNMT) machinery, we compared the expression levels of DNMT1, DNMT3a and DNMT3b mRNAs between the high β and low β groups of breast tumors." (PMID 20830311, 2010). "Previous study indicated that DNMT1, DNMT3A, and DNMT3B are upregulated in breast tumor tissues compared with normal breast tissues." (PMID 36982660, 2023).
cognitive decline (10 papers, 2014 to 2025). "Associations of DNMT3A genetic mutations with cognitive decline and late-onset AD risk have also been reported." (PMID 37891690, 2023). "It was also found that intracerebroventricular injection of miR-29c mimic into 5xFAD mice prevented cognitive decline, as well as neuronal loss in the subiculum area, by down-regulating Dnmt3a and Dnmt3b in the hippocampus." (PMID 34750393, 2021). "Since the loss of 5-mC is a well-known hallmark of aging brain and the loss of DNMT1 and DNMT3a proteins is known to trigger a cognitive decline in mice, these findings may indicate a premature impact of DNA methylation disturbances on SAMP8 mice cognition." (PMID 30619445, 2018). "An association was discovered between the rs1187120 SNP in DNMT3A and annual decline in cognitive functioning, suggesting that DNMT3A moderates cognitive decline in subjects with mild cognitive impairment." (PMID 26703582, 2015). "Interestingly, recent work in AD mouse models demonstrated that transplantation of TET2-mutant, but not DNMT3A-mutant, bone marrow-derived cells reduced cognitive decline and Aβ production, suggesting a causal association between TET2-mutations, clonal hematopoiesis, and cognitive resilience." (PMID 41293128, 2025).